C20orf141 (chromosome 20 open reading frame 141)
Synonyms: dJ860F19.4
Tractability: Antibody: UniProt predicts a signal peptide or a membrane-spanning region; the Human Protein Atlas places it where antibodies can reach.
Gene: Protein-coding gene on chromosome 20 (2,814,987 to 2,815,833, forward strand). Ensembl gene ENSG00000258713.
Subcellular location: Membrane
Subcellular location (Human Protein Atlas): Plasma membrane; Vesicles
Gene Ontology:
Molecular function: protein binding
Cellular component: membrane
Genetic constraint (gnomAD): Loss-of-function variants: 11 observed, 9.23 expected, observed/expected ratio (o/e) 1.19, 90% interval 0.74 to 1.82. That is too few expected variants to judge how well the gene tolerates losing a copy. Missense variants: 220 observed, 204.7 expected, observed/expected ratio (o/e) 1.07, 90% interval 0.96 to 1.2. Synonymous variants: 101 observed, 93.15 expected, observed/expected ratio (o/e) 1.08, 90% interval 0.92 to 1.28.
Homologues: Orthologues: chimpanzee C20H20orf141 (98% identical), macaque C10H20orf141 (93% identical), pig C20orf141 (76% identical), dog C20orf141 (72% identical).